BCL2 (BCL2 apoptosis regulator)
Diseases named in the same sentence as BCL2 in open-access papers (continued):
Sharing a sentence is not in itself a finding about the gene and the disease.
cancer (continued). "Cancer cells with IDH mutations depend on abnormally increased BCL-2 expression, which protects them from apoptosis." (PMID 39063158, 2024). "In many cancers, upregulation of HoxA1 has been associated with the suppression of apoptosis via upregulation of the anti-apoptotic genes Bcl2 and BAX, and the promotion of proliferation via upregulation of Cyclin D128,29." (PMID 38365890, 2024). "By providing a detailed characterization of mutation-induced effects on Bcl-2, this study lays a foundation for future experimental validation and the development of targeted anti-cancer strategies, including rational drug design." (PMID 39840282, 2024). "Targeted FASN depletion primes cancer cells for mitochondrial apoptosis as it synergizes with BCL-2/BCL-XL-targeting BH3 mimetics to render cancer cells more susceptible to T-cell-mediated killing." (PMID 39349429, 2024). "A promoter SNP in the Bcl-2 gene, the -938C>A genotype (rs2279115), is identified to be associated with high Bcl-2 gene expression and is related to some cancer developments." (PMID 39205918, 2024). "It targets cancer-causing genes such as BCL2, MCL1, and CDK6, and its reduction leads to increased cell growth and resistance to cell death." (PMID 39061157, 2024). "This overexpression of bcl-2 is a hallmark of various cancers, promoting their progression by initiating angiogenesis and enhancing cell survival." (PMID 39624842, 2024). "Elevated BCL-2 expression is associated with poor prognosis in various cancers, emphasizing its significance in cancer development and treatment outcomes." (PMID 39193333, 2024). "For instance, the largest cluster comprising all cancer types contained 212 samples, out of which 160 had mutations in BCL2." (PMID 39040139, 2024). "Dysregulation of Bcl2 expression or function is implicated in various diseases, including cancer, where overexpression of Bcl2 can confer increased cell survival and resistance to apoptotic stimuli." (PMID 38738026, 2024). "Dysregulation of the bcl2 gene and overexpression of the BCL2 protein have been implicated in the development and progression of various cancers." (PMID 39767775, 2024). "Increased expression of Ube2l6 is linked to degradation/suppression of cancer cells and affected downstream apoptotic factors (i.e. Caspase 3, Caspase 9, Bcl-2, Bax)." (PMID 38650655, 2024). "The loss of miR-34 leads to increased levels of BCL2, which inhibits programmed cell death (apoptosis) and allows cancer cells to survive under conditions that would normally induce cell death." (PMID 39452836, 2024). "As a result, Bcl-2 dysregulation has been linked to the development of various disorders, including cancer, autoimmune and cardiovascular diseases." (PMID 38169388, 2024). "It is shown that the downregulation of three genes (miR-210, 23b and Bcl-2) was linked to promoting apoptosis, autophagy and senescence in cancer." (PMID 38732643, 2024). "Apoptosis, which is a key hallmarkof cancer, is associated with the deregulation of the balance betweenproapoptotic proteins and antiapoptotic proteins such as BCL-2,BCL-xl,BFL-1, BCL-w, BRAG-16, and MCL-1." (PMID 38882173, 2024). "In order to understand the antilymphoma properties of the acyclic terpenoids Gg, PT and FA and how they affect U-937 cells, we decided to study three potential targets associated with cancer, including Bcl-2, Mcl-1 and VEGFR-2." (PMID 38731446, 2024). "The findings underscore the pivotal role of Bcl-2 mutations in disrupting apoptotic regulation, a hallmark of cancer, and highlight their potential as diagnostic biomarkers and therapeutic targets." (PMID 39840282, 2024).
cancer (continued). "Curcumin nanoparticles exhibited significantly higher cytotoxicity against MCF-7 cancer cells, which was associated with Bcl-2 down-regulation and Bax and caspase 3 up-regulation-induced apoptosis." (PMID 37237914, 2023). "Western blot analysis revealed that LMW-F reduced the phosphorylation of Bcl-2 at Thr 56, which was associated with the prevention of anti-apoptotic activity of cancer cells." (PMID 38186578, 2023). "EGCG-induced apoptosis of cancer cells has been linked with a substantial decrease in Bcl-2 expression, caspase-8 activation, and proteolytic cleavage of Bid in glioblastoma cells." (PMID 36836619, 2023). "The A allele is reported to be associated with increased cancer risk by increasing the expression level of Bcl-2 and inhibiting apoptosis." (PMID 36879307, 2023). "Several studies have linked the overexpression levels of the anti-apoptotic Bcl-2 protein with resistance to chemotherapy, radiation treatment, and targeted therapies in many cancer types." (PMID 37834104, 2023). "We observed that IMP3 down-regulation shows a protective effect toward cancer progression and identified the underlying molecular mechanism based on the control of Bcl-2 and Bcl-xL transcripts, two key mediators of the intrinsic apoptotic pathway." (PMID 37024466, 2023). "The inhibition of Bcl-2 is insufficient to estimate the significance and magnitude and predict the outcome of the cancer suppression abilities associated with the LAB treatments." (PMID 36613399, 2023). "The B cell lymphoma 2 (Bcl-2) family proteins that appropriately regulate apoptotic cell death are associated with the progression and development of several cancers." (PMID 36838574, 2023). "The presence of phenolic compounds in various plant extracts was associated with the inhibition of cancer cell growth through increased Bax and decreased Bcl2 expression." (PMID 37512080, 2023). "Particularly, the upregulation of anti-apoptotic proteins, such as Bcl-2, Bcl-xL, Mcl-1 and surviving, is associated with cancer progression, tumorigenesis and treatment resistance." (PMID 37686541, 2023). "The high activation of Bcl-2, which exhibits anti-apoptotic effects, has been associated with the occurrence, progression, and prognosis of cancer." (PMID 37637038, 2023). "A number of antiapoptotic factors contribute to apoptosis deficiency in cancer cells, with a special focus on antiapoptotic Bcl-2 proteins, such as Bcl-2, Bcl-xL, Bcl-w, and Mcl-1." (PMID 36902392, 2023). "The synonymous mutations in BCL2 are enriched in its anti-apoptotic domain and likely play a role in cancer cell proliferation." (PMID 38062391, 2023). "Another family of proteins frequently mutated in cancer is BCL2, informally known as “guardians of cell death”." (PMID 37457123, 2023). "Genes involved in endocrine resistance pathways primarily fell into 3 functional categories: ERBB2/IGF1R, CCND1, and BCL2, which have been reported to be associated with endocrine resistance and an increased risk of cancer recurrence in breast cancer." (PMID 37328469, 2023). "The delayed pressure endurance managed by imperfect apoptosis occurs in cancer cells by either increased anti-apoptotic genes Bcl-2 and Bcl-xL or deficiency in pro-apoptotic genes Bax and Bak." (PMID 37119445, 2023). "Numerous studies have shown that BA, OA, and UA cause significant fold changes in the BAX/Bcl-2 expression ratio in various cancer cells." (PMID 36615613, 2023). "It has also been reported that the overexpression of Bcl-2 is associated with drug resistance and a poor clinical outcome in patients with various cancer types, and Bcl-2 has been considered as a potential cancer therapy target." (PMID 37587470, 2023).
cancer (continued). "Intense research into finding out the new cancer treatment targets has led to the identification of Bcl-2 overexpression as a hallmark for cancer and Bcl-2 inhibition as a possible cancer treatment approach." (PMID 36838574, 2023). "First, RTA dh404 promoted or inhibited genes associated with cancer cell apoptosis, including three genes (Apaf-1, Bcl-2, and BCL-XL) in GBM8401 cells and three genes (NOXA, BCL-XL, and FADD) in U87MG cells." (PMID 36835414, 2023). "Navitoclax is an inhibitor of BCL-2 protein families, which are often overexpressed in cancer and associated with drug resistance." (PMID 37251536, 2023). "The overexpression of Bcl-2 and underexpression of Bax, resulting from the genetic variants of the encoded genes, have been linked to the development of these cancers." (PMID 37232720, 2023). "B-cell lymphoma 2 (Bcl2), an important cancer-associated regulator, plays a crucial role in cell apoptosis 17, and its presence or absence determines the susceptibility of cancer cells to chemotherapy." (PMID 37151875, 2023). "The association between BCL2 gene expression and cancer is complex and can vary depending on the specific cancer type and context." (PMID 38067251, 2023). "From the point of view of cancer therapy, the suppression of mutant bcl2 genes encoding anti-apoptotic proteins of the same family is an attractive solution." (PMID 36614277, 2023). "Bcl-2 is a crucial regulator of apoptosis linked to cancer, making it a possible target for anti-cancer therapy." (PMID 36979608, 2023). "In this regard, apoptosis evasion via the over-expression of Bcl-2 or Bcl-XL has recently been proposed as a hallmark of cancer." (PMID 36993955, 2023). "In pancreatic cell lines, 17 reduced the expression of the anti-apoptotic protein, Bcl-2, and increased the pro-apoptotic protein, cytochrome C, which indicates the activation of intrinsic apoptosis, the primary cause of cancer cell death." (PMID 37376026, 2023). "BCL2 expression has been associated with both positive and poor prognostic outcomes in different cancers." (PMID 38067251, 2023). "In the present paper, we will suggest an analytical model for entropy creation and ergodicity during chromothripsis; we will also present a computational model for the mutation of the BCL2 gene responsible for apoptosis in cancer cells." (PMID 38248163, 2023). "Specifically, the integral outer mitochondrial membrane protein encoded by BCL2 can block the apoptotic death of many cells like lymphocytes, making it a prognostic biomarker for cancers." (PMID 35269511, 2022). "To confirm the reduced proliferative and survival effect in NAT10‐deficient cancer cells, we performed expression analysis of some cell proliferation genes such as BCL2, p16, and p21." (PMID 36149760, 2022). "miR-630 has different gene targets among them are those associated with cancer phenotype such as BCL2, YAP-1 and Slug." (PMID 35248081, 2022). "DAPK1 expression induced autophagy and apoptotic activity in various cancers by causing autophagic cell death via reducing the interaction between Beclin-1, Bcl-2, and Bcl-XL." (PMID 35321516, 2022). "The ratio of Bax to Bcl-2 appears to play an important function in modulating cancer cell apoptosis susceptibility." (PMID 36309655, 2022). "Bcl-2 is a member of the Bcl-2 apoptosis-modulating protein family, and its impairment has been associated with a variety of cancers." (PMID 35756648, 2022).
cancer (continued). "In comparison with the genetic variants, we characterized at the Bcl‐2 protein level to demonstrate the cancer cells can acquire resistance ability by increasing the Bcl‐2 expression." (PMID 34910369, 2022). "The Bcl-2 family is a large group of proteins consisting of pro-apoptotic proteins BAX, BAK, and the BH3-only subfamily, along with anti-apoptotic members such as Bcl-2, Bcl-xL, and Bcl-W, many of which are implicated in cancer development." (PMID 35163485, 2022). "BCL2 is a pivotal antiapoptotic protein, overexpression of which is associated with cancer cell sensitivity to drugs including sorafenib." (PMID 35970393, 2022). "The Bax/Bcl-2 ratio determines cell susceptibility to apoptosis and high Bax/Bcl-2 ratio indicates the enhanced apoptosis of cancer cells." (PMID 36091590, 2022). "An excessive expression of Bcl-2 and a suppressed expression of Bax lead to homeostatic disbalance of cells, subsequently causing cancer." (PMID 35402265, 2022). "The evasion of apoptosis is a hallmark of cancer, and the B-cell lymphoma-2 (BCL2) protein family plays a critical role in regulating intrinsic apoptosis." (PMID 36171613, 2022). "Bcl-2- and Bax-mediated pro-apoptotic signaling also plays a crucial role in skeletal muscle atrophy associated with cancer, denervation, and pressure-induced injury." (PMID 36588738, 2022). "The most common pathway used by cancer cells to evade apoptosis is based on the upregulation of antiapoptotic BCL-2 proteins and the loss of BAX/BAK proteins; indeed, BCL-2 gene overexpression is present in over half of all cancers." (PMID 36291779, 2022). "Alternatively, genistein caused alterations of anti-apoptotic proteins, including Bcl-2 and cFLIP, resulting in disruption of survival signaling, cancer proliferation, and induction of cancer cell apoptosis." (PMID 35892954, 2022). "The gene expression of proapoptotic (Bax and Caspase-3) and cancer-associated genes which promote cell survival (Bcl-2, Survivin, EGFR, and VEGF) were analyzed in RT-PCR." (PMID 35578215, 2022). "Precisely, nisin causes an imbalance in the expression of BAX/BCL-2 expression ratio and a higher expression of the pro-apoptotic proteins at the messenger ribonucleic acid (mRNA) and protein level of the cancer cells." (PMID 36230679, 2022). "The overexpression of the Bcl-2 oncogene with the inhibition of the Bax proapoptotic factor is associated with a good prognosis in many types of cancer." (PMID 36145353, 2022). "Evading apoptosis is a key hallmark of cancer, owing to the aberrant expression of pro-survival BCL-2 proteins governing the intrinsic apoptotic pathway." (PMID 36358660, 2022). "It has also been shown that obatoclax displayed BCL-2 associated x protein/BCL-2 antagonist killer (BAX/BAK) dependent anti-cancer efficacy by inducing mitochondrial apoptosis." (PMID 34989664, 2022). "This is as expected as the first two are well known markers of proliferation associated with cancer growth while a decrease in BCL2 expression is associated with loss of apoptosis and increased proliferation." (PMID 36612143, 2022). "Previous research has shown an increase in the level of BCL2 in numerous cancer types, including PC, and is associated with apoptosis resistance and cancer metastasis." (PMID 34959269, 2021). "The nanoparticles efficiently promoted cancer cell apoptosis by regulating the B cell CLL/lymphoma 2 (BCL2), BCL2-associated X protein BAX, cleaved caspase-3, matrix metalloproteinase (MMP)-2, and MMP-9 pathways." (PMID 33925605, 2021).
cancer (continued). "Resistant cells express higher levels of Bcl-2 and overexpression of Bcl-2 typically results in cancer cell resistance which is associated with abnormal changes in PI3K/AKT pathways." (PMID 34572902, 2021). "This extract inhibited the expression of Bcl-2 and thereby caused the activation of caspase-3, 7, 8, and 9 in these cancer cells." (PMID 33916780, 2021). "Efforts to mitigate this cancer hallmark have been ongoing for decades, focused mostly on inhibiting BCL-2, a key anti-apoptosis effector." (PMID 34198580, 2021). "So far, promoter polymorphism of BAX -248 G>A and BCL2 -938 C>A are two of the most studied polymorphisms reported being associated with the increased risk of cancers." (PMID 33906310, 2021). "The capability of Bcl-2 to balance the action of healthy characterized oncoproteins such as Myc underlies an extremely pivotal theory in cancer biology." (PMID 34638779, 2021). "Our study was reliable with the tissue-specific association of BAX -248 G>A and BCL2 -938 C>A polymorphisms in the context of the global cancer prognosis." (PMID 33906310, 2021). "The bcl-2 (b cell lymphoma 2) protein encoded by BCL2 is a major apoptosis regulator and has mainly antiapoptotic effects in many different cancer entities." (PMID 33919527, 2021). "Among the genes affected by the most common unique variants, BCLAF1 is the best-studied in the cancer setting as an associated transcription factor for Bcl2." (PMID 35008243, 2021). "The compound induces S-phase cell cycle arrest and subsequent apoptosis in cancer cells, with an associated downregulation of Bcl-xL and Bcl-2, and an upregulation of Bax and cytochrome C." (PMID 34769512, 2021). "WA also augments the susceptibility of cancer cells towards apoptosis by dissipating Bcl-2/Bax and Bcl-2/Bim ratios." (PMID 34946778, 2021). "It was found that Bcl-2 exerted an anti-apoptotic effect and Bcl-2 upregulation was linked to poor prognosis in many cancers." (PMID 34170852, 2021). "The Western blot analysis of MDA-MB-468 cells treated with 14i showed a significant change in Bcl-2-associated X protein (Bax)/B-cell lymphoma 2 (Bcl-2) ratio and activation of caspase-3, which play a critical role in cancer cell apoptosis." (PMID 35011463, 2021). "Given the anti-apoptotic properties of Bcl-2, upregulation of this factor is often linked to cancer cell resistance to paclitaxel." (PMID 33802861, 2021). "Bcl-2 siRNA and genistein combination caused more than an 80% decrease of cell proliferation in malignant neuroblastoma SK-N-DZ cells in humans." (PMID 34336089, 2021). "Since evading of apoptosis is a classical hallmark of cancer, and venetoclax (a BCL2 inhibitor) has shown clinical benefit in combination with tamoxifen, we argue that drugs inducing apoptosis should be considered to be included in the treatment regimen." (PMID 33530335, 2021). "The ratio of Bax/Bcl-2 is sometimes applied as the prognostic marker and susceptibility of a particular cancer treatment to cancer patients." (PMID 34299604, 2021). "Bcl-2 and Survivin have been extensively implicated in the development of chemoresistance in cancer." (PMID 34503172, 2021). "BCL2 encodes an anti-apoptotic protein important in maintaining cell survival and its expression is dysregulated in many cancers, allowing cells to bypass cell cycle checkpoints and contribute to cancer initiation and progression." (PMID 33513764, 2021). "Although MCL-1 was the last of the key cancer-associated BCL-2 pro-survival proteins targeted with BH3-mimetics, several potent MCL-1-specific compounds have now been reported." (PMID 34515749, 2021).